TNF (tumor necrosis factor)
Diseases named in the same sentence as TNF in open-access papers (continued):
Sharing a sentence is not in itself a finding about the gene and the disease.
endometriosis (continued). "Increased concentrations of TNF-α in endometriosis patients are involved in angiogenesis and inflammation, and the level of TNF-α along with glycodelin is associated with the severity of menstrual pain." (PMID 37893241, 2023). "Studies from endometriosis mouse models found elevated levels of Tumor Necrosis Factor-alpha (TNFα), interleukin 6 (IL-6), Macrophage Inflammatory Protein 1 alpha (MIP-1α), and MIP-2 in peritoneal macrophages." (PMID 36693853, 2023). "Circumin treatment has been shown to significantly increase the expression of selected miRNAs in ESCs from endometriosis patients, which also downregulates the expression of TNFα and the phosphorylations of the AKT, ERK, and NF-κB signaling pathways." (PMID 37834449, 2023). "TNF-α, IL-1, and IL-6 participate in the development of endometriosis, and carcinogenesis of the endometrium." (PMID 36834426, 2023). "Inflammatory cytokines (interleukin-1β (IL-1β), interleukin-6 (IL-6), insulin-like growth factor (IGF-1) and tumour necrosis factor-α (TNF-α) are observed to be at a higher concentration in the peritoneal fluid of people with endometriosis." (PMID 38002684, 2023). "After the analysis, it was detected that the levels of IL-6, IL-10, IL-13, and TNF-α were significantly higher in women with endometriosis and infertility (P < 0.05)." (PMID 38601772, 2023). "There are increased levels of pro-inflammatory cytokines, such as TNF-α, IL-1β, IL-6, and IL-17A, in the PF and ectopic lesions of patients with endometriosis, promoting the inflammation and development of endometriosis." (PMID 36865552, 2023). "Here, we demonstrated that endometriosis in rats caused the activation of NLRP3 and NF-κB pathways as well as the increase in levels of IL-1β and TNF-α, while fisetin inhibited the activation of NLRP3/NF-κB as well as diminished the levels of IL-1β and TNF-α." (PMID 36982152, 2023). "In inflammatory situations, progesterone receptors are downregulated under effect of TNF-α, and progesterone resistance develops, leading to endometriosis." (PMID 38868448, 2023). "Peritoneal fluid of patients with endometriosis found prostaglandins, levels of activated macrophages, tumor necrosis factor (TNF) ±, IL-1β, and increased proteases." (PMID 36268444, 2022). "TNF-α also plays a critical role in local and systemic manifestations of endometriosis, as it stimulates the proliferation of endometriotic stromal cells by inducing IL-8 expression and improves the adhesion of endometrial stromal cells to mesothelial cells." (PMID 36555618, 2022). "Administration of HBOT for 2 hr a day in 6 wk on endometriosis-induced rats has demonstrated a significant lowering effect of the TNF-α level, leading to a remission of the endometriosis lesion due to the inhibition of NFκB." (PMID 35911854, 2022). "The levels of inflammatory factors (like CRP, IL-6, IL-8, and TNF-a) in the peripheral blood and peritoneal fluid of patients with endometriosis are increased." (PMID 35800055, 2022). "Tumor necrosis factor alpha (TNF-α) is a proinflammatory cytokine that plays a role in endometriosis by stimulating adhesion of endometrial cells and their ectopic proliferation." (PMID 36359004, 2022). "Subsequently, enrichment analysis showed altered molecular mechanisms in the CCs of patients with endometriosis I/II; Cytokine-cytokine receptor interactions, Chemokine signaling, TNF signaling, NOD-like receptor signaling, and NF-kappa B signaling." (PMID 35388025, 2022). "The aim of this study was to investigate the association of TNF-α (G-308 A), IL-1β (C+3954T) and IL1-Ra intron 2 VNTR polymorphisms with the risk of endometriosis in Mexican mestizo women." (PMID 36028805, 2022). "IL-8 and TNF-α were among the cytokines whose higher expression levels were noted in the peritoneal fluid of women with endometriosis." (PMID 35805112, 2022).
endometriosis (continued). "In this study, we investigated the association of TNF-α (G-308A), IL-1β (C+3954T) and IL-1Ra (intron 2, VNTR) polymorphisms and endometriosis in Mexican mestizo women from Mexico City and its surroundings." (PMID 36028805, 2022). "Studies have shown the promise of using IL-1β and TNF-α for the prediction of endometriosis, with specificities of 0.85 and 0.72, respectively." (PMID 36555618, 2022). "Several molecular mechanisms have been pointed out for endometriosis, including inhibiting TNF-α-induced cellular apoptosis and enhancing NALP-3-induced IL-1β production." (PMID 36354688, 2022). "While the underlying mechanisms of the IL family and TNF in endometriosis have been well studied, the IFN signaling pathways in endometriosis are not fully understood." (PMID 36358904, 2022). "In the study of human endometriosis, progesterone (10−6 mol/L) was found to be effective in attenuating TNFα/estrogen-induced expression of CXCL8 in endometriotic stromal cells." (PMID 35476705, 2022). "The prevalence of TNF*2-allele heterozygotes (p = 0.025; OR 3.8), TNF*2-allele (p = 0.029; OR 3.4), IL1B*2-allele heterozygotes (p = 0.044; OR 2.69) and its carriage rate (p = 0.041; OR 2.64) in endometriosis stage IV was higher than the CTR group." (PMID 36028805, 2022). "Inflammation-related pathways such as IL6-JAK/STAT3 signaling, inflammatory response, interferon α response, interferon γ response, and TNFα signaling via NF-κB, were found to be significantly upregulated in patients with endometriosis." (PMID 36339397, 2022). "Several cytokines are elevated in the peritoneal fluid and in the serum of patients with endometriosis; however, the cytokines IL-1β, TNF-α, IL-6, and IL-10 play a fundamental role in the pathogenesis of endometriosis." (PMID 35807280, 2022). "Up-regulation was also detected in the spinal cord of mice with induced endometriosis, whilst TNF-α was the only upregulated cytokine found in the posterior insula." (PMID 35052864, 2022). "The results show that treatment SR-16234 significantly reduced the level of proinflammatory cytokines, namely TNF-α and IL-1β, in the endometriosis-like lesions." (PMID 35885010, 2022). "Endometriosis induced by LPS administrations resulted in an increase in NFκB, tumor necrosis factor alpha (TNF-α) and a reduction in IL-1 in Lf-treated animals." (PMID 35889882, 2022). "The peritoneal fluid and serum of patients with endometriosis and adenomyosis were found to have elevated levels of inflammatory cytokines, including IL-6, IL-8, IL-1b, IFN-γ, and TNF-α, which was associated with natural killer (NK) cell dysfunction." (PMID 35022045, 2022). "Some studies also suggested that anti-TNF-α or TNF-inhibitors can significantly inhibit the progression of endometriosis lesions." (PMID 35784295, 2022). "In animals with laparoscopically confirmed endometriosis, blockading TNF-α with p55-soluble TNF-α receptors results in inhibition of progression and growth of endometriotic implants." (PMID 36359004, 2022). "In endometriosis, local proinflammatory mediators such as interleukin (IL)-1b and tumor necrosis factor- (TNF-) a stimulate the nuclear factor kB (NF-κB) and hypoxia inducible factor- (HIF-) 1a signaling pathways, increasing COX-2 expression." (PMID 35059465, 2022). "In the peritoneal cavity of endometriosis patients, the immune cells are recruited and secrete excessive levels of proinflammatory cytokines (interleukin (IL)-1, IL-6, TNF, and IFNγ), which promote disease development and progression." (PMID 36358904, 2022). "In endometriotic lesions, TNFα activates NF-κB and inflammasome signaling to enhance endometriosis progression." (PMID 36358904, 2022). "The inflammatory cytokines, TNF-α and IL-1β, play crucial roles in triggering the inflammatory pathway and are upregulated in the peritoneal fluid of women with endometriosis." (PMID 36428561, 2022).
endometriosis (continued). "Consumption of TFA increases circulating levels of inflammatory markers such as IL-6 and TNF-α, which are involved in endometriosis pathogenesis." (PMID 36138433, 2022). "There is also an increase in the proinflammatory and anti-inflammatory cytokines IL-1, IL-4, IL-6, IL-8, IL-10 and TNFα in the serum and in peritoneal fluid of women with endometriosis, particularly in advanced stages." (PMID 35888644, 2022). "Laboratory studies have shown that peritoneal macrophages in women with endometriosis express cytokines IL-6, IL-1B, and tumor necrosis factor more than in women with benign abnormalities." (PMID 36381357, 2022). "Several studies have shown that TNF-α levels are significantly elevated in the peritoneal fluid of women with endometriosis, and it stimulates the proliferation of endometriotic stromal cells (ESCs)." (PMID 36428561, 2022). "We suggest that drugs targeting this gene should be studied in cohort-scale clinical trials for repurposing in endometriosis, such as infliximab (known as anti-TNF biologics)." (PMID 35401535, 2022). "The markers related to the pathogenesis of endometriosis in ESCs were evaluated using estradiol, tumor necrosis factor alpha (TNF-α), interleukin 1β (IL-1β), and IL-32, administered alone or in combination with DNG." (PMID 36428561, 2022). "For example, higher follicular MIP-1α (CCL3) and CD44 were correlated with polycystic ovary syndrome and IL-23, IFN-γ, and TNF-α correlated with endometriosis." (PMID 34868029, 2021). "Much as we found high levels of TNF‐α in our study, they also concluded that TNF‐α is an important factor in advancement of endometriosis." (PMID 34557653, 2021). "Nevertheless, the production of serum TNF-α, a pro-inflammatory cytokine, was notably upregulated in the mice with endometriosis, which was partly downregulated by rhIL-37 treatment." (PMID 34429116, 2021). "A positive effect of drugs inhibiting the action of TNF on the development of endometriosis has been shown in animal models." (PMID 34945174, 2021). "Tumor necrosis factor α (TNF-α), a key factor in the inflammatory immune response, is involved in the endometriosis development." (PMID 34639133, 2021). "Nevertheless, contradictory results for levels of IL-10, IL-1β, IL-2 and TNF-α in the peritoneal fluid of women with endometriosis has been also reported." (PMID 34639133, 2021). "In rats with induced endometriosis, quercetin administration significantly decreased endometrial implants’ size and serum E2 and TNF-α level compared to the related control group." (PMID 33919512, 2021). "In investigating its efficacy, an in-silico study was conducted to determine Propolis active components that can interact with endometriosis-related receptors such as TNF-alpha, NF-κB, estrogen, progesterone, and prostaglandin receptors." (PMID 34194730, 2021). "Naringenin prevented endometriosis propagation via anti-inflammatory mechanisms by modulating the serum TNF-α, NO level, and proapoptotic effects as ROS overproduction and the loss of mitochondrial membrane potential." (PMID 33919512, 2021). "Although their study considered only human cases; the final result was parallel to our findings of an increase in peritoneal levels of TNF‐α in animals with endometriosis." (PMID 34557653, 2021). "Increased amounts of prostaglandins, activated macrophages, IL-1, IL-6, IL-10, and tumor necrosis factor alpha (TNF-α) have been found in the PF of patients with endometriosis when compared to the PF of control groups." (PMID 34900746, 2021). "Topological analysis demonstrated that major targets of S. Stoloniferum include IL-8, EGFR, TNF, and VEGFA, which are several of the causal genes of endometriosis." (PMID 33804660, 2021). "TNF-α secreted by activated macrophages has potent inflammatory, cytotoxic, and angiogenic properties and is involved in the development of endometriosis." (PMID 34616540, 2021).
endometriosis (continued). "Some articles have demonstrated that TNF-α has an important role in the development of endometriosis." (PMID 34901283, 2021). "Inflammation was assessed using the peritoneal concentration of TNF‐α and serum levels of IL‐37 as crucial inflammatory markers in endometriosis." (PMID 34557653, 2021). "In this study, they found that TNF-α, detected abundantly in the peritoneum of women with endometriosis, cooperates indirectly with ER-β to incite these events." (PMID 34073257, 2021). "TNF-α concentration in the follicular flow of patients with endometriosis who have poor oocyte quality is thought to trigger the secretion of other pro-inflammatory cytokines, which ultimately interfere with the process of oocyte fertilization." (PMID 34475699, 2021). "Negative results were also observed when analyzing the productions of IFN-γ and TNF-α by CD4+ T cells in the endometriosis group compared with the control group." (PMID 34531861, 2021). "The concentrations of pro-inflammatory interleukins (ILs) (i.e. IL-6, IL-1β, and IL-10) and tumor necrosis factor-alpha (TNF-α) were increased in patients with endometriosis." (PMID 34475699, 2021). "Naringenin ameliorated the expression of VEGF, reduced the volume of the endometriosis lesions and decreased serum levels of TNF-α in rats after 21 days of administration." (PMID 33804660, 2021). "According to some studies, the level of TNF-α increased in patients with endometriosis and correlated with the severity of the disease." (PMID 34201813, 2021). "The concentration of pro-inflammatory cytokines like tumor necrosis factor-α (TNF-α) was highly expressed in the peritoneal fluid of the patients with endometriosis." (PMID 34429116, 2021). "Increased activation of macrophages in peritoneal fluid in patients with endometriosis leads to the upregulation of proinflammatory factors, such as IL-1β, IL-6, IL-8, and TNF-α, which create favorable conditions for their occurrence." (PMID 33574880, 2021). "This study showed that letrozole combined with dydrogesterone can significantly reduce the levels of VEGF, CA125, E2, P, IL-6, and TNF-a in patients with endometriosis compared with the control group." (PMID 34901283, 2021). "Interlieukin-10 (IL-10, IL-6, IL-8, COX2 (cyclooxygenase-2)), VEGF, and tumor necrosis factor α (TNF-α) are upregulated in the peritoneal fluid of endometriosis." (PMID 34204039, 2021). "It has been reported that TNF-α is present in the peritoneal cavity of patients with endometriosis, and its levels are significantly higher in the early stages of the pathology." (PMID 34639133, 2021). "Previous reports have shown that several inflammatory cytokines, such as IL-6, interleukin-8 (IL-8), and tumor necrosis factor-α (TNFα), were significantly elevated in the peritoneal fluid of patients with endometriosis." (PMID 34872568, 2021). "TNF‐α can also induce the proliferation, differentiation, and migration of endometrial cells during endometriosis." (PMID 34557653, 2021). "The same group of scientists examined the effect of resveratrol on VEGF and TNF-α expression in the eutopic endometrium of infertile patients with endometriosis within the implantation window in a randomized exploratory trial." (PMID 33919512, 2021). "Proinflammatory cytokines such as IL-1, IL-6, and TNF-alpha stimulate the synthesis of CRP which are found to be overexpressed in women with endometriosis as compared to controls." (PMID 34754275, 2021). "Existing data suggests that miR-191 suppresses TNFα-induced cell death in ectopic endometrium from endometriosis patients." (PMID 33804660, 2021). "To investigate the role of NLRC5 in inflammation in endometriosis, we first identified the role of TNF-α in NLRC5 in EESCs." (PMID 33013364, 2020). "Consistent evidence indicates that women with endometriosis have a higher level of TNF-α in their peritoneal fluid and endometrium." (PMID 32121467, 2020).
endometriosis (continued). "Due to often described elevation of peritoneal TNFα in endometriosis by us and others, blockers of TNFα, such as etanercept, leflunomide, and infliximab, were evaluated in preclinical models and in small randomized clinical trials." (PMID 32429215, 2020). "Although inflammatory cytokines such as TNFα are elevated in the peritoneal cavity in painful endometriosis, TNFα antagonists are yet to show clinical efficacy." (PMID 32153361, 2020). "Several authors demonstrate an increased level of TNFα in peripheral fluid and endometrium of women with endometriosis and detected a positive correlation between TNFα concentrations and endometriotic lesion size." (PMID 32325785, 2020). "Inflammatory dysregulation, such as increased TNFα and transforming growth factor-beta signaling, plays a vital role in endometriosis’s pathogenesis." (PMID 33233463, 2020). "Our previous research suggested that oestrogen that up‐regulated in endometriotic lesions enhanced the expression of IL‐6 and TNF‐α via p38 MAPK pathway resulting in inflammatory response to promote endometriosis." (PMID 32725958, 2020). "They found that IL-6, IL-10, IL-13, and TNF-α are highly expressed in the peritoneal fluid of endometriosis patients." (PMID 33354460, 2020). "Interlieukin-10 (IL-10, IL-6, IL-8, COX2 (cyclooxygenase-2), VEGF (vascular endothelial growth factor) and tumor necrosis factor α (TNF-α) have been observed to be increased in the peritoneal fluid of endometriosis." (PMID 32244563, 2020). "Lastly, the tumour necrosis factor-alpha (TNF-α) signalling pathway was significantly enriched as one of the biological mechanisms underpinning endometriosis and migraine in the present study." (PMID 32121467, 2020). "This was suggested to be partly due to a peritoneal increase in other pro-inflammatory factors, such as TNF-alpha and IL-1, in endometriosis patients." (PMID 32604857, 2020). "As a result, TNF-α activates systemic and local inflammatory mechanisms in endometriosis development and progression, including elevated levels of chemokines and pro-inflammatory cytokines." (PMID 32145751, 2020). "Our functional enrichment analyses reveal some genetically controlled biological pathways underlying endometriosis and migraine including interleukin-1 receptor binding, focal adhesion-PI3K-Akt-mTOR-signaling, MAPK and TNF alpha signalling." (PMID 32121467, 2020). "According to in vivo results, the expression of MMP2 seems to be unaffected by TNFα treatment, both in HESCs prepared from healthy patients (HE-HESCs) and from women with endometriosis (EE-HESCs)." (PMID 32325785, 2020). "In the recent original research published on International Journal of Fertility and Sterility the association between tumor necrosis factor-alpha (TNF-α) genetic polymorphisms and endometriosis in 150 Iranian patients suffered this disease." (PMID 32112641, 2020). "Curcumin can target the TNF-α expression to improve the growth differentiation factor-9 (GDF-9) expression in peritoneal fluid of women with endometriosis." (PMID 32244563, 2020). "Nevertheless, octyl gallate in this study did not appear to reduce TNF-α levels as it was evident by the average of TNF-α levels in the rats administered with octyl gallate which increased compared to the surgically-induced endometriosis rats." (PMID 32685413, 2020). "Studies have identified increased angiogenic factors, including VEGF and TNFα, in the pelvic peritoneal fluid of patients with endometriosis." (PMID 33132854, 2020). "Increased TNF-α secreted from inflammatory cells affects the early stage of endometriosis via activating local or systemic inflammation, and also has toxic effects on CA neurons." (PMID 32145751, 2020).